INS (insulin)
Diseases named in the same sentence as INS in open-access papers (continued):
Sharing a sentence is not in itself a finding about the gene and the disease.
Obesity (continued). "Decreased insulinaemia due to lowered GSIS protects B-Atgl-KO mice from diet-induced obesity, improves insulin sensitivity, increases lipid mobilisation from WAT and causes BAT activation." (PMID 27677764, 2016). "Lifestyle factors, such as obesity and unhealthy eating habits, as well as increased age disturb redox balance in the body and influence insulin sensitivity." (PMID 27071614, 2016). "Obesity prevalent in T2D is strongly associated with higher BMD probably through mechanical loading and hormonal factors including insulin, estrogen, and leptin." (PMID 27777961, 2016). "In this review, we explore the complex mechanisms that link lipid metabolism, inflammation, insulin signaling, and obesity." (PMID 27098727, 2016). "The aim of the present study was to investigate the relationships between the plasma AA profile and the type/degree of obesity as well as glucose and insulin regulation, in normoglycemic Japanese adults." (PMID 26788116, 2016). "Elevating, we found that several SNPs associated with DNA methylation show impact on metabolic phenotypes in the studied cohort, including obesity measurements, glucose- and insulin traits, as well as lipid profiles." (PMID 27322064, 2016). "We show that Ames dwarf mice fed HFD for 12 weeks had an increase in subcutaneous and visceral adiposity as a result of diet‐induced obesity, yet are more insulin sensitive and have higher levels of adiponectin compared to control mice fed HFD." (PMID 26990883, 2016). "In the present study, we found that the insulin-resistant condition and obesity were developed at week 12 after HFD consumption." (PMID 26830020, 2016). "A Spanish cross-sectional study on cardiovascular risk factors in 6 to 8 year-old schoolchildren found some of the same metabolic consequences of obesity as in adults (elevated triglycerides, insulin, HOMA-IR, and lower HDL-cholesterol)." (PMID 27590045, 2016). "Experimental infection of mice with the nematode Nippostrongylus brasiliensis lowered obesity and blood lipid levels, increased anti-inflammatory and immune regulatory activity, and improved insulin sensitivity." (PMID 27666719, 2016). "As a result, after 3 weeks of high fat diet, mice with muscle-specific overexpression of IL-10 develop obesity, but remain insulin sensitive in skeletal muscle." (PMID 27746742, 2016). "Our results do not support the recommendation of an LCHFD for use in prediabetes; rather interventions aimed specifically at reducing obesity and improving insulin sensitivity should be pursued." (PMID 26878317, 2016). "The participants with obesity were significantly more insulin resistant compared to the lean group, determined by the M value." (PMID 27437034, 2016). "Many factors, such as insulin/leptin dysregulation and inflammation, mediate the effect of obesity and cognition and motor behaviors." (PMID 26881095, 2016). "There is robust research evidence indicating that obesity is a key determinant of insulin secretion and resistance to the effects of insulin." (PMID 27232339, 2016). "An advanced understanding of the physiological and pathophysiological actions of leptin and insulin in the CNS will shed light on potential therapeutic interventions for obesity." (PMID 27812350, 2016). "In contrast, the suppression of beta-oxidation or selective scavenging of mitochondrial H2O2 preserves skeletal muscle insulin sensitivity in models of diet-induced obesity." (PMID 27537847, 2016). "In this study, the SD group showed features consistent with obesity development, i.e., significant increase in body weight, fat mass, adipose tissue inflammation, and serum total cholesterol, cLDL, leptin and insulin concentrations." (PMID 27656148, 2016). "In this study of healthy non-diabetic pregnant women, we found that women with isolated hypothyroxinaemia have worse metabolic parameters with increased obesity, glycaemia, triglycerides and insulin resistance compared to euthyroid women." (PMID 26586839, 2016).
Obesity (continued). "This means that dietary intervention and increased physical activity can significantly help to improve insulin sensitivity and obesity in women living with PCOS." (PMID 27672393, 2016). "Adipose tissue and skeletal muscle are the main targets for the action of insulin and major contributors to insulin resistance in states of obesity." (PMID 27527335, 2016). "Adiponectin concentrations were lower in insulin-resistant states such as obesity and type 2 DM and pregnancy complicated by GDM." (PMID 27651836, 2016). "This is exemplified by studies demonstrating that tissue‐restricted loss of function of key insulin signalling nodes actually extends health span of mice and that insulin per se can promote the progression of obesity‐related metabolic dysfunction." (PMID 27137487, 2016). "The biphasic glucose curve in our SHR.BN16 strain is consistent with observations from human studies showing that a biphasic glucose curve is related to more favorable indices for obesity and insulin sensitivity." (PMID 27031336, 2016). "Adipokines, which are secreted from adipose tissues, are important regulators for adipogenesis, insulin sensitivity, and obesity." (PMID 26797605, 2016). "In contrast, omentin, identified in the human omental adipose depot, regulates blood glucose level by enhancing insulin action and is decreased in obesity." (PMID 27148161, 2016). "Taken together, our findings suggest that SIRT3 positively regulates endothelial insulin sensitivity and show that SIRT3 deficiency and resultant increased mtROS contribute to vascular dysfunction in obesity." (PMID 27000941, 2016). "In this regard, PTP1B knockout mice increases sensitivity to leptin and insulin, and are resistant to a high-fat diet-induced obesity." (PMID 27812350, 2016). "In patients with anorexia nervosa and varying stages of obesity, Irisin was positively correlated with BMI, fat mass, body cell mass, fat free mass and insulin levels." (PMID 27472279, 2016). "This enzyme was previously identified as a priority drug target, as DGAT1 mutant mice are viable and show numerous beneficial metabolic characteristics such as resistance to diet-induced obesity and increased insulin or leptin sensitivity." (PMID 27428418, 2016). "Obesity is described as a chronic andsystemic inflammatory disease as a result of the release of enormouspro-inflammatory cytokines and increasing insulin insensitivity." (PMID 27284905, 2016). "High molecular weight adiponectin is expressed in white adipose tissue, increases insulin sensitivity, and is downregulated in obesity." (PMID 26971100, 2016). "Recent studies suggest that β cell proliferation is required for β cell expansion in obesity and in times of increased insulin demand because most β cell expansion is mediated by self-replication." (PMID 27226575, 2016). "Although overproduction of NO in overweight and obesity has mainly been attributed to increased inducible NOS (iNOS) activity in response to insulin and pro-inflammatory cytokines." (PMID 27213443, 2016). "White adipocytes contribute to the whole body insulation and have endocrine functions including secretion of leptin, TNF-α, adiponectin, resistin, and other compounds related to the degree of obesity and insulin sensitivity." (PMID 27073398, 2016). "Horses with EL had higher resting serum insulin and triglyceride concentrations and high body condition scores (obesity) compared with healthy horses." (PMID 27684374, 2016). "Here, we observe that mice with chronic AMPK activation, resulting from mutation of the AMPK γ2 subunit, exhibit ghrelin signaling-dependent hyperphagia, obesity, and impaired pancreatic islet insulin secretion." (PMID 27133129, 2016). "Obesity leads to elevated expression of insulin, estrogen, growth factors, inflammatory cytokines and adipokines, which promote ovarian cancer cell proliferation, survival, metastasis, angiogenesis and reduced apoptosis in cancer cells." (PMID 27074576, 2016).
Obesity (continued). "Obese Leprdb/db Ks mice on the control diet had similar circulating insulin levels as lean animals despite severe obesity and hyperglycemia —a manifestation of severe β-cell failure." (PMID 27110686, 2016). "Insulin and leptin resistance are seen as the interface between inflammation and metabolism in obesity-related CVD." (PMID 27598982, 2016). "ApoA-I was reported to improve insulin sensitivity and exert anti-inflammatory, anti-obesity effect in animal studies." (PMID 26911989, 2016). "There is also strong evidence that β cells are dynamically active cells, which, under specific conditions such as obesity, can increase in size and subsequently increase insulin secretion." (PMID 27092078, 2016). "The anti-obesity and insulin-sensitizing actions of adiponectin are mediated by its receptors occurring in two isoforms, adipoR1 and adipoR2." (PMID 27528227, 2016). "Leptin is one of the highly studied molecules in obesity after insulin (present in7.4% of total abstracts)." (PMID 26886906, 2016). "The cellular level of DsbA-L is negatively correlated with obesity in mice and human, and its expression is stimulated by insulin sensitizer rosiglitazone but inhibited by the inflammatory cytokine TNF-α." (PMID 27795806, 2016). "A previous study has reported that insulin protects diabetic rats from obesity-induced hepatic ER stress." (PMID 27104558, 2016). "In cases of T2DM, the beneficial effects of (−)-catechin in the treatment of obesity-related diseases were also observed, with enhanced insulin-dependent glucose uptake in differentiated adipocytes." (PMID 27092490, 2016). "The findings demonstrate that a transient early postnatal overweight induces early-onset (P21) obesity, accompanied by activation of pulmonary adipocytokine/insulin signaling and increased pulmonary expression of pro-asthmatic IL-6, IL-13, IL-17A and Tnf-α." (PMID 27087690, 2016). "The altered adipokine profile in obesity leads to profound changes in insulin sensitivity and various metabolic derangements." (PMID 26930652, 2016). "Diet-induced obesity can also influence insulin resistance in the hippocampus and likely elsewhere in the brain where insulin receptors are expressed, such as the amygdala and midbrain (McNayet al., 2010)." (PMID 27303627, 2016). "In clinical studies, treatment with NSAIDs enhanced many biochemical indices such as blood glucose level, glucose uptake, insulin clearance, CRP, lipid profile associated with obesity, and T2DM." (PMID 27527213, 2016). "Even though adipocytes become insensitive to insulin-dependent glucose uptake during obesity, insulin is able to enhance adipocyte MCP-1 gene expression levels aggravating the influx of monocytes." (PMID 26940592, 2016). "Pla2g1b−/− mice show resistance to obesity, lower plasma insulin and leptin levels, and improved glucose tolerance when fed a high-fat/carbohydrate diet." (PMID 29259680, 2016). "Transgenic mice expressing human non-steroidal anti-inflammatory drug activated gene 1 (NAG-1) have less adipose tissue, improved insulin sensitivity, lower insulin levels and are resistant to dietary induced obesity." (PMID 26745373, 2016). "Obesity, in particular abdominal obesity, alters the composition of plasma and tissue fatty acids (FAs), which contributes to inflammation and insulin resistance." (PMID 27023786, 2016). "These mice have a lower mitochondrial content in type I fibers and the mice develop obesity and impaired insulin sensitivity." (PMID 27411515, 2016). "We next assessed the impact of the late-onset obesity on glucose homeostasis and insulin sensitivity." (PMID 27138914, 2016). "A chronic low-grade inflammatory status in obesity is known to induce impaired insulin signaling, glucose intolerance, and insulin resistance." (PMID 27087690, 2016). "Obesity is associated with excess lipid storage in white adipose tissue (WAT), adipokine dysregulation, insulin resistance, and chronic low-grade inflammation." (PMID 27023786, 2016).
Obesity (continued). "Both, insulin and leptin have been considered the key players linking obesity, autonomic derangement, and sympathetically mediated diseases (e.g. hypertension)." (PMID 26781642, 2016). "Leptin uptake and insulin secretion were found controlled by miR-200a, miR-200b, and miR-429, which are related to obesity." (PMID 27147943, 2016). "This study evaluated the variation in insulin sensitivity in women living with polycystic ovarian syndrome in relation to obesity." (PMID 27672393, 2016). "This study was conducted aiming to evaluate maternal levels of adipokines and insulin in pregnancies complicated by overweight and obesity and its correlations with maternal and fetal outcomes." (PMID 27651836, 2016). "We also demonstrated that Lf levels in T2D subjects were comparable to those of insulin-sensitive individuals, at least to metabolically healthy subjects characterized by severe obesity." (PMID 27902700, 2016). "At 40 weeks, as expected with obesity, R299Q γ2 mice displayed glucose intolerance and reduced insulin sensitivity." (PMID 27133129, 2016). "It is well known that abnormal lipid metabolism in obesity is regarded as a major driving force for dyslipidemia and hepatic steatosis, and insulin resistance and inflammation play an important role in the development of dyslipidemia and hepatic steatosis." (PMID 27213439, 2016). "We show that a short-term oral administration of sodium butyrate was able to alleviate obesity and increase insulin sensitivity through promotion of skeletal muscle mitochondrial function and fatty acid oxidation." (PMID 27528227, 2016). "It is well known that obesity is obviously related to insulin level, metabolic syndromes, and cardiovascular diseases, to which WAT accumulation and BAT dysfunction contributed tremendously." (PMID 26903879, 2016). "The circulating levels of insulin and signaling pathway are altered in obesity; this interacts with inflammatory processes to modulate cognition and behaviors." (PMID 26881095, 2016). "Decreased insulin response to glucose, dyslipidaemia, and obesity frequently progress into overt type 2 diabetes with a decline in β-cell function, sustained hyperglycaemia, and increased advanced glycation end products (AGE) formation." (PMID 27073398, 2016). "Obesity arises through the dysregulations of intracellular lipid metabolism or extracellular lipid partitioning among tissues, and the perturbation of intracellular/extracellular lipases variably and often profoundly affect obesity and insulin resistance." (PMID 29259680, 2016). "The shared phenotypes of aripiprazole and mice with impaired LEP/LEPR function like “obesity”, “insulin resistance” and “glucose tolerance impaired” point to alterations of leptinergic signalling by the antipsychotic aripiprazole." (PMID 27673331, 2016). "The relationships between insulin gene dosage and obesity has previously been explored in male and female Ins2-/- mice with full or reduced Ins1 dosage, as well as in female Ins1-/- mice with full or partial Ins2 dosage." (PMID 27055260, 2016). "Compared to control group, patients of the CAD group have an increased percentage of obesity, MetS, hypertension, insulin and BMI, TG, and LDL-C levels (all p < 0.05)." (PMID 27004807, 2016). "Second, we explored what the consequences of the long-day-induced obese state are for glucose and insulin tolerance, to establish if this is a useful model of ‘healthy obesity’." (PMID 27736740, 2016). "Overall, these results demonstrate that an alternating diet improves obesity-related hepatic steatosis and insulin sensitivity." (PMID 27189661, 2016). "In the context of obesity, low grade inflammation has been suggested to contribute to the development of insulin and leptin resistance." (PMID 27410967, 2016). "Map4k4 promoted islet expansion in obesity, and islets derived from Map4k4 iKO mice demonstrated reduced insulin secretion ex vivo." (PMID 27226575, 2016).
Obesity (continued). "The rising incidence of obesity in patients with T1D has been shown to be related to the use of intensive insulin therapy to maintain tight glycemic control." (PMID 27375900, 2016). "It was shown that five gavage doses of SB significantly alleviated HF diet-induced obesity and restored plasma glucose, insulin and leptin to control levels." (PMID 27528227, 2016). "Leptin and insulin actively participate in energy metabolism and their elevations in blood correlate with metabolic disturbance in rodent models of obesity." (PMID 27582541, 2016). "It is difficult to pinpoint the sole effects of insulin in vivo during the development of obesity, as changes in many other circulating factors accompany hyperinsulinaemia." (PMID 26940592, 2016). "N-3 PUFA also have a number of metabolic effects including improvement in insulin secretion, sensitivity and anti-obesity action." (PMID 27565734, 2016). "Serum irisin has been found to be higher and related to insulin in acanthosis nigricans-related obesity." (PMID 27472279, 2016). "The activation of both BAT and beige adipocytes by cold stimulation, medication or lifestyle can improve insulin sensitivity and potentially protect against obesity and other metabolic diseases." (PMID 26903879, 2016). "Male offspring of dams injected with lipopolysaccharide during mid-gestation had enhanced food intake, increased body weight and enlarged abdominal adipose tissue with reduced insulin uptake, consistent with development of obesity and insulin resistance." (PMID 26858656, 2016). "The reason for the increase in the fasting and 2-hour plasma glucose with age is likely due to an increase in the peripheral insulin resistance, age-related deterioration in β-cell function, physical inactivity, sarcopenia and obesity." (PMID 27570971, 2016). "We also examined plasma concentrations of leptin, which has postulated roles in obesity and insulin action." (PMID 27134637, 2016). "The significant correlations between many of the traits highlights the relatedness of the phenotypic measures that serves to define an individual signature of obesity and insulin sensitivity in response to chronic HFD feeding in adult females." (PMID 27811965, 2016). "Coen and colleagues 8 have demonstrated higher concentrations of selected saturated ceramides, including C14:0, C16:0, and C18:0 in insulin‐resistant versus insulin‐sensitive postmenopausal women with obesity." (PMID 26916476, 2016). "All these alterations evidence an impairment in glucose metabolism and insulin signalling due to increased fat intake, a well-known effect of HF-diet-induced obesity, and which is also characteristic of MONW subjects." (PMID 27885970, 2016). "Both leptin and insulin biomarkers are used as predictors of weight gain and obesity during infancy." (PMID 27440187, 2016). "A number of previously reported data have shown a correlation between vaspin levels and insulin sensitivity and obesity indices." (PMID 27462373, 2016). "There is some evidence that vaspin has the potential to increase adipocyte insulin sensitivity and to suppress obesity through promoting the differentiation of 3T3-L1 preadipocytes by decreasing IL-6 mRNA and increasing GLUT-4 mRNA levels." (PMID 27462373, 2016). "While clear associations between these genes and DN are not yet elucidated, their involvement in important biochemical pathways of insulin metabolism, oxidative stress, and obesity, suggest they have important influences on renal injury." (PMID 27855634, 2016). "IL-37-overexpressing mice showed improved response to insulin and increased glucose tolerance and were protected from obesity." (PMID 27148268, 2016). "In humans and animal models, obesity reduces insulin clearance, probably due to lower IDE expression and activity in the liver." (PMID 27467214, 2016).